CYP2C19 (cytochrome P450 family 2 subfamily C member 19)
Diseases named in the same sentence as CYP2C19 in open-access papers (continued):
Sharing a sentence is not in itself a finding about the gene and the disease.
diabetes (37 papers, 2013 to 2026). "This study employs the ABCD-GENE score (age, body mass index, chronic kidney disease, diabetes, and CYP2C19 variants) to compare the effectiveness and safety of clopidogrel versus ticagrelor-based DAPT in ACS patients post-PCI." (PMID 40567366, 2025). "This study analyzed the risk factors of premature CI and found that CYP2C19 IM + PM phenotype, history of smoking, hypertension, diabetes mellitus, and dyslipidemia were risk factors for premature CI." (PMID 39472784, 2024). "It means that young and middle-aged adults with CYP2C19 loss-of-function variants and traditional risk factors (smoking, hypertension, diabetes mellitus, and dyslipidemia) need to be aware of the risk of developing CI." (PMID 39472784, 2024). "History of smoking, hypertension, diabetes mellitus, dyslipidemia, and CYP2C19 IM + PM phenotypes were independently associated with premature CI susceptibility." (PMID 39472784, 2024). "In summary, history of smoking, hypertension, diabetes mellitus, dyslipidemia, and CYP2C19 IM + PM phenotypes were independently associated with premature CI susceptibility." (PMID 39472784, 2024). "The proportion of overweight, diabetes mellitus, and β-blockers administered was higher in CYP2C19 LOF allele carriers among smokers." (PMID 36760562, 2023). "The ABCD-GENE risk score confirmed a proposition of clinical and genotype components to identify patients at HRPR on clopidogrel in different populations with age, BMI, CKD, diabetes, and CYP2C19 LOF alleles." (PMID 35387342, 2022). "Those were CYP2C19 genetic polymorphism, proton‐pump inhibitor usage, and comorbidities (diabetes mellitus and chronic kidney disease)." (PMID 33641235, 2021). "Estimated risk of clopidogrel resistance in patients with at least one of the following risk factors: CYP2C19*2, CYP2C19*3, smoking, diabetes mellitus, increase in platelet count adjusted for age and sex." (PMID 25329996, 2014). "The ABCD-GENE score, which integrates age, body mass index (BMI), chronic kidney disease (CKD), diabetes, and CYP2C19 genetic variants, was developed as a pragmatic clinical tool to identify patients at elevated risk for high on-treatment platelet reactivity (HPR) when receiving clopidogrel therapy." (PMID 40567366, 2025). "The combination of clinical factors (age, BMI, CKD and diabetes) with CYP2C19 genetic variants likely captures both the pharmacokinetic and pharmacodynamic aspects of antiplatelet response, advancing the application of precision medicine in cardiovascular disease management." (PMID 40567366, 2025). "Comorbidities may also cause phenoconversion, for example diabetes is known to be associated with decreased CYP2C19 function." (PMID 37808344, 2023). "In detail, loss-of-function polymorphisms of the cytochrome P450 isoenzymes CYP2C9 and CYP2C19, advanced age, diabetes, and concomitant treatment with morphine, calcium channel blockers, or the proton pump inhibitor omeprazole were associated with an attenuated response to clopidogrel therapy." (PMID 28425039, 2017). "Furthermore, the proposed model also shows indirect and direct impact of several variables on clinical outcome: ACS, diabetes mellitus, CYP2C19*2 and CYP2C19*17 genetic variants independently predicted HTPR." (PMID 25051347, 2014). "Our study suggests a pathway, which might explain indirect and direct impact of variables on clinical outcome: ACS, diabetes mellitus, CYP2C19*2 and CYP2C19*17 genetic variants independently predicted HTPR." (PMID 25051347, 2014). "The study also revealed regionally enriched variants with clinically important impacts including CYP2C19 (drug metabolism), HBB (thalassemia risk), and SLC30A8 (diabetes susceptibility)." (PMID 40898550, 2025). "The proportion of individuals with diabetes mellitus in CYP2C19 IM group was higher than those in CYP2C19 EM and PM groups (41.5% vs. 33.3% and 34.9%, p = 0.008)." (PMID 39472784, 2024).
diabetes (continued). "Diabetes mellitus is recently identified as a modifying factor of CYP2C19 activity, with patients displaying mean reduced activity of ∼50%." (PMID 37361233, 2023). "Of the donors, 12.5% suffered from an additional liver disease, 17.5% from a chronic inflammatory disease, 12.5% patients had diabetes mellitus and 5% of patients used CYP2C19 inhibitors before surgery." (PMID 37361233, 2023). "Simultaneous application of cinnamon and metformin can modulate the function of CYP2C19 to the observed level in the control group and make it more predictable to treat diabetes mellitus and fate of drugs that are metabolized by this enzyme." (PMID 32742601, 2020). "In the linear regression models with diabetes as a dichotomous variable, gender seemed to influence significantly CYP2C19 duodenal mRNA levels with higher expression in female subjects (β = 1.28, p = 0.01)." (PMID 31269743, 2019). "The weighted PREDICT score includes ACS, diabetes mellitus, left ventricular function, renal failure, age and CYP2C19*2 genotype, ranging a maximum of 165 points." (PMID 25051347, 2014). "Our model indicates that the two genetic variants CYP2C19*2 and *17 as well as the two clinical variables ACS and diabetes mellitus explain only 7% of the variability in platelet inhibition by clopidogrel." (PMID 25051347, 2014). "The paths from genetic polymorphisms of CYP2C19*2 and *17 (hetero or homozygote) as well as from clinical characteristics as ACS on admission and diabetes mellitus were independent predictors of HTPR (path coefficients: 0.17, -0.10, 0.11 and 0.10." (PMID 25051347, 2014). "HRPR can reflect genetic polymorphism at cytochrome P450 2C19 (CYP2C19), but more commonly results from acquired alterations in CYP2C19 expression, possibly related to age, obesity, diabetes, left ventricular dysfunction, concurrent medications, or inflammation." (PMID 37520136, 2023). "In addition to CYP2C19 genotype, comorbidities such as diabetes and obesity are important factors in determining appropriate anti-platelet therapy." (PMID 35647265, 2022). "The study found that patients who had diabetes and no-function CYP2C19 variants had the highest incidence of recurrent ACS and maximum platelet aggregation when administered clopidogrel compared to all other groups." (PMID 35647265, 2022). "Therefore, this study aims to examine the association between CYP2C19 and CYP2D6 metabolic phenotypes and the risk of diabetes mellitus in UK Biobank participants taking antidepressants and antipsychotics." (PMID 34828364, 2021). "The simultaneous administration of cinnamon and metformin can modulate the function of CYP2C19 to the observed level in the control group (i.e., healthy rats) and makes it more predictable to treat diabetes mellitus and the levels of other drugs that this enzyme is involved in their metabolism." (PMID 32742601, 2020). "Thus, it is very important to evaluate diabetes-induced changes in the activity of CYP2C19, as one of the most important metabolic enzymes." (PMID 32742601, 2020). "Two clinical characteristics (ACS and diabetes mellitus) and two genetic variants (CYP2C19*2 and CYP2C19*17) independently predicted HTPR but not MACE." (PMID 25051347, 2014). "Diabetes and cardiometabolic diseases are highly associated with NAFLD5–9 and therefore these data further support the hypothesis that NAFLD is involved in reduced clopidogrel efficacy through the downregulation of CYP2C19." (PMID 36927865, 2023). "Eight patients (20%) exhibited CYP2C19 IM/PM phenotypes that were not predicted by their CYP2C19 genotype, of which six could be linked to the presence of diabetes or liver disease." (PMID 37361233, 2023). "The result of this research indicated that diabetes could significantly reduce the activity of CYP2C19 (by ~50%) since the mean metabolic ratios of omeprazole was changed from 0.091±0.005 in the control group to 0.054±0.005 in the untreated diabetic rats (P-value=0.003)." (PMID 32742601, 2020).
diabetes (continued). "Also, the influence of covariates was evaluated (age, weight, body mass index (BMI), obesity defined as BMI ≥ 30 kg/m2, sex, diabetes mellitus, co-administration of PPI or statins, presence of CYP2C19*2, CYP2C19*17, CYP3A4*1G alleles, and ABCB1 3435 TT genotype)." (PMID 28914344, 2017). "As the CYP2C19*2 genotype may only account for about up to 12% of the clopidogrel response, the higher percentages may only be found in homogeneous populations, other relevant factors such as diabetes or age may play a role, too." (PMID 23981380, 2013). "For several of the antidepressants investigated, we consistently found that the interaction of diabetes status and CYP2D6 and CYP2C19 metabolic phenotype is statistically significant." (PMID 34828364, 2021). "In conclusion, the findings of this study clearly show that a large fraction of persons with diabetes are exposed to drugs or drug combinations for which there exist PGx-based dosing guidelines related to CYP2D6, CYP2C19, and SLCO1B1." (PMID 34577599, 2021). "By using of the following four factors: diabetes mellitus, ACS, CYP2C19*2 and CYP2C19*17 a cumulative score was formed and applied on the total patient cohort to analyze its predictive value for HTPR." (PMID 25051347, 2014). "Diabetes mellitus (OR: 2.1; 95%CI: 1.2–3.6; p = 0.011), ACS (OR: 1.5; 95%CI: 1.2–1.9; p = 0.006) and CYP2C19*17 genotype (OR: 0.54; 95%CI: 0.30-0-97; p = 0.038) emerged as HTPR predictors." (PMID 25051347, 2014). "In detail, Diabetes was weighed by factor 2, ACS by factor 1, CYP2C19*2 by factor 1 and CYP2C19*17 by factor -1 (DACC score)." (PMID 25051347, 2014). "The frequency of DGI as recently reported for CYP2D6, CYP2C19 and SLCO1B1 further implies that a significant proportion of persons with diabetes will have phenotypes for which actions in principle should be taken regarding dose adjustment or avoidance of the given drugs." (PMID 34577599, 2021). "Diabetes positively regulates APP (4 references; q = 0.00015), NLRP3 (19 references; q = 0.00168), and PVT1 (4 references; q = 0.00755), while negatively regulating CYP2C19 (14 references; q = 0.00372), suggesting its influence on pathways related to inflammation, immune response, and metabolism." (PMID 40881172, 2025). "The consistent directionality and statistical significance observed in the regulation of APP, NLRP3, PVT1, and CYP2C19 suggest the possibility of a Diabetes → gene → HNSCC pathway, in which diabetes-related gene alterations may contribute to HNSCC pathogenesis." (PMID 40881172, 2025). "Antibiotic resistance is one of multiple factors implicated in H. pylori treatment failure, along with comorbidities such as diabetes mellitus, cigarette smoking, CYP2C19 metabolizer genotype, and non-adherence to therapy; however, it remains the most significant." (PMID 35208776, 2022). "Diabetes and obesity may have an additive effect along with no-function CYP2C19 genotypes on clopidogrel treatment failure." (PMID 35647265, 2022). "This information collectively suggests that metabolic comorbidities like obesity and diabetes, which are highly correlated with NAFLD, are not the primary drivers of the observed CYP2C19 downregulation." (PMID 36927865, 2023).
transient ischemic attack (25 papers, 2018 to 2025). A brief attack (from a few minutes to an hour) of cerebral dysfunction of vascular origin, with no persistent neurological deficit. "The subgroup analysis of CHANCE and subsequent meta-analysis showed that the presence of CYP2C19 LoFA was associated with the decreased efficacy of clopidogrel in the treatment of acute ischemic stroke or transient ischemic attack (TIA)." (PMID 33685396, 2021). "This prespecified subgroup analysis of the randomized clinical CHANCE-2 trial investigates whether the efficacy and safety of ticagrelor-aspirin vs clopidogrel-aspirin are consistent with the expected degree of CYP2C19 loss-of-function after transient ischemic attack or minor stroke." (PMID 37279000, 2023). "The metabolism of clopidogrel by the isoenzyme CYP2C19 is inhibited by CBD, which could lead to lower levels of the active metabolite and increase the risk for transient ischemic attacks." (PMID 38978789, 2024). "For stroke, a large randomised controlled trial (RCT) showed that absence of the CYP2C19 no-function allele in patients with a minor ischaemic stroke or transient ischaemic attack (TIA) predicted better effectiveness of clopidogrel plus aspirin over aspirin alone." (PMID 38550953, 2023). "Studies on antiplatelet effect of ticagrelor/aspirin and clopidogrel/aspirin in patients with acute minor stroke and transient ischemic attack (TIA) stratified by CYP2C19 metabolizer status is limited." (PMID 33411687, 2020). "At the same time, it was proposed that in the CYP2C19 LoFA population, such as ESRS ≥3, clopidogrel still had a significant effect on acute ischemic stroke or transient ischemic attack." (PMID 33685396, 2021). "A Chinese study found that ticagrelor plus aspirin treated patients with transient ischaemic attack (TIA) or minor stroke had lower platelet activity than those treated with clopidogrel, especially CYP2C19 LoFA carriers." (PMID 33121452, 2020).
epilepsy (20 papers, 2010 to 2025). A brain disorder characterized by episodes of abnormally increased neuronal discharge resulting in transient episodes of sensory or motor neurological dysfunction, or psychic dysfunction. "Our objective was to describe the association between CYP2C9 and CYP2C19 genetic polymorphisms and adverse reactions induced by antiseizure medications among Peruvian patients with epilepsy." (PMID 41471361, 2025). "The objective of this study was to describe the association between CYP2C9 and CYP2C19 polymorphisms and ADRs induced by antiseizure medication in Peruvian patients with epilepsy." (PMID 41471361, 2025). "The present study describes the allelic variants of CYP2C9 and CYP2C19, evaluating their association with ADRs induced by ASMs in Peruvian patients with epilepsy." (PMID 41471361, 2025). "The allele frequencies of CYP2C9*2, CYP2C9*3, CYP2C19*2, CYP2C19*3, and CYP2C19*17 were 3.4%, 3.4%, 14%, 0%, and 3%, respectively, among patients with epilepsy in the present study." (PMID 41471361, 2025). "In the Asian populations, 55.4% of Japanese patients of epilepsy carry the CYP2C19 variant with 13–23% poor metabolites in Asian populations and 2%-5% in white and black populations." (PMID 35290166, 2022). "The CT genotype of the rs1799853 CYP2C9 polymorphism and the GA genotype of the rs4244285 polymorphism of the CYP2C19 gene were shown to result in an increased risk of epilepsy." (PMID 34769124, 2021). "The aim of this study is to better understand and provide further knowledge about the metabolism and interactions between phenobarbital and CYP2C19 polymorphisms in children with epilepsy, interplay between sleep, and EVs." (PMID 31689970, 2019). "The clearance of phenobarbital was shown to be 18.8% lower in CYP2C19 PMs, compared to other CYP2C19 genotypes, in 74 Japanese patients with epilepsy, in which carriers of the defective CYP2C9 allele(s) were excluded." (PMID 27713373, 2010). "However, this observational study is the first to describe the allelic variants of CYP2C9 and CYP2C19 associated with adverse reactions in patients with epilepsy from a reference hospital in the coastal area of Callao, Peru." (PMID 41471361, 2025). "It has also been shown that the occurrence of C-G-A haplotype in relation to the polymorphism rs1799853 of the CYP2C9 gene and the polymorphism rs4244285 of the CYP2C19 gene may be associated with a reduced risk of epilepsy." (PMID 34769124, 2021). "The results obtained indicate that the polymorphisms rs1799853 and rs1057910 CYP2C9 and the polymorphism rs4244285 CYP2C19 may be associated with the occurrence of drug-resistant epilepsy in children." (PMID 34769124, 2021). "Genetic polymorphism of cytochrome P450 genes, such as CYP2C9 and CYP2C19, is especially known for drug resistance in epilepsy patients and it may be the reason that such genes are highly targeted by current AEDs." (PMID 31801232, 2019). "We here review the studies on the effects of CYP2C9 and CYP2C19 on the plasma concentration of PHT in the treatment of epilepsy." (PMID 35290166, 2022). "The influences of the CYP2C9 and CYP2C19 genotypes on the population clearance estimates for phenobarbital were also evaluated in 79 Japanese patients with epilepsy." (PMID 27713373, 2010). "In this cohort of Peruvian patients with epilepsy, the reduced-function alleles CYP2C9*2, CYP2C9*3, and CYP2C19*2, associated with decreased metabolic activity, were significantly linked to an increased risk of adverse drug reactions induced by antiseizure medications." (PMID 41471361, 2025). "The developmental characteristics, CYP2C19 genotype, concomitant medications, and liver and kidney function indicators of the children with epilepsy were considered potential factors affecting the pharmacokinetic characteristics of CLB and N-CLB and analyzed using a PPK modeling approach." (PMID 40733022, 2025). "Subjects with epilepsy can be classified based on the ability to metabolize CYP2C19 substrates." (PMID 31689970, 2019).
epilepsy (continued). "A recent population pharmacokinetic study in 287 Chinese patients with epilepsy showed that CYP2C9 in combination with CYP2C19 genotypes significantly influenced the pharmacokinetic variability of valproic acid, as quantified by population pharmacokinetic analysis." (PMID 27713373, 2010). "In addition, CYP2C19*2 (rs4244285; 681G>A) and CYP2C19*3 (rs4986893; 636G>A) are associated with changes in the volume of distribution and plasma concentrations of VPA and its metabolites in patients with epilepsy." (PMID 36677060, 2023). "Therefore, it is recommended that when VPA is used in the treatment of epilepsy, the dosage should be increased for patients with CYP2C19*3 GG genotype showing fast metabolism, while the dosage be appropriately reduced for patients with CYP2C19*3 AA genotype." (PMID 35290166, 2022). "For epilepsy patients, SDEA should be used with caution when taking Phenytoin and Valproic acid (metabolized by CYP2C19) at the same time, in order to avoid serious adverse reactions." (PMID 36874034, 2023). "An experimental study showed an overexpression of CYP3A4, CYP2C9, and CYP2E1 in human brain microvascular endothelial cells of drug‐resistant patients with epilepsy while CYP2D6 and CYP2C19 were downregulated." (PMID 34560816, 2022). "The influence of CYP2C19 and CYP3A5 genotypes on the population clearance estimates of zonisamide were assessed in 99 Japanese patients with epilepsy." (PMID 27713373, 2010). "In another analysis of 169 patients with epilepsy from Taiwan, a clinically relevant decrease in the maximal rate of metabolism (Vmax) and intrinsic clearance was observed when the patients were CYP2C9 hetero EMs in combination with CYP2C19 hetero EMs or PMs." (PMID 27713373, 2010). "In contrast to CYP2C19, the CYP3A5*3 genotype did not affect the clearance of zonisamide, indicating that CYP3A5*3 genotypes do not have a major impact on the zonisamide pharmacokinetics in Japanese patients with epilepsy." (PMID 27713373, 2010).